CD200R1 (CD200 receptor 1)
Diseases named in the same sentence as CD200R1 in open-access papers (continued):
Sharing a sentence is not in itself a finding about the gene and the disease.
rheumatoid arthritis (8 papers, 2020 to 2025). A chronic, systemic autoimmune disorder characterized by inflammation in the synovial membranes and articular surfaces. "Aberrant expression of CD200R1 was shown to contribute to abnormal Th17 cell differentiation and chemotaxis in patients with rheumatoid arthritis." (PMID 36253751, 2022). "The decrease in CD200R1 expression has been documented in SLE, rheumatoid arthritis, inflammatory bowel disease, etc.." (PMID 36556186, 2022).
Autoimmunity (7 papers, 2012 to 2024). The occurrence of an immune reaction against the organism's own cells or tissues. "In this context, several studies to date have shown that the CD200:CD200R1 pathway exhibits an immunosuppressive effect on the inflammatory cellular response and contributes to the reduction of severity in animal models of inflammation and autoimmunity." (PMID 30195773, 2018). "CD200 receptor 1(CD200R1) signalling limits myeloid cell responses and reduces autoimmunity, alloimmunity and viral‐mediated immunopathology, but has never been examined in the context of eosinophilic inflammation." (PMID 31365119, 2019).
influenza (7 papers, 2012 to 2025). An acute viral infection of the respiratory tract, occurring in isolated cases, in epidemics, or in pandemics; it is caused by serologically different strains of viruses (influenzaviruses) designated A, B, and C, has a 3-day incubation period, and usually lasts for 3 to 10 days. "CD200R1 is expressed on alveolar macrophages and lung DC while CD200 is expressed on epithelial cells, and mice deficient in CD200 show increased mortality and delayed resolution of airway inflammation following influenza infection." (PMID 22984588, 2012). "In the case of influenza and meningococcus, CD200−/− mice are prone to the effects of inflammation/sepsis, indicating that CD200R1:CD200 interaction is not likely to be involved in the regulation of cellular anti-viral mechanisms." (PMID 23082204, 2012).
systemic lupus erythematosus (7 papers, 2012 to 2022). An autoimmune multi-organ disease typically associated with vasculopathy and autoantibody production. "In addition, this down-regulation of CD200R1 expression on DCs was also noted in lupus-prone mice along with elevated levels of anti-dsDNA Abs, which could be reversed by CD200-Fc treatment possibly through reducing the productions of IL-6 and IL-10 from DCs." (PMID 31597242, 2019). "We therefore evaluated the functional status of CD200/CD200 receptor 1 (CD200R1) interactions in subjects with systemic lupus erythematosus (SLE)." (PMID 22621248, 2012). "Abnormal expression of CD200/CD200R1 may contribute to the immunologic abnormalities in patients with systemic lupus erythematosus (SLE)." (PMID 27545083, 2016). "This study suggests that the immunosuppressive CD200/CD200R1 signaling pathway might be involved in the immunopathology of NZB/WF1 mice; the present results merit further exploration of agents that can modulate the CD200/CD200FR1 pathway as a therapy for human lupus." (PMID 27545083, 2016).
Arthritis (5 papers, 2012 to 2026). Inflammation of a joint. "Rather, the local microenvironment, particularly CD200+ fibroblasts, acted as gatekeepers of arthritis, engaging the checkpoint receptor CD200R1 on migrating CD2+MHC-II+CCR2+ myeloid precursors." (PMID 41482544, 2026). "After treatment with agonistic anti-CD200R1, arthritis was significantly reduced on day 21, supporting the critical anti-inflammatory signaling mediated by CD200." (PMID 41482544, 2026). "Fourth, we used IL-23OE in the arthritis-susceptible BALB/c inbred strain and intervened every 5 days with an agonistic anti-CD200R1 treatment (OX-110) starting on day 7 to restore the suppression of skin-derived precursors by resident CD200+ fibroblasts." (PMID 41482544, 2026). "Cross-linking of CD200R1 with CD200-Fc fusion protein reduces the inflammation in arthritis model animals, and inhibition of CD200R1 by antibody reduces virus-induced cytokine storm." (PMID 34952004, 2022).
ischemia (5 papers, 2014 to 2021). A hypoperfusion of the BLOOD through an organ or tissue caused by a PATHOLOGIC CONSTRICTION or obstruction of its BLOOD VESSELS, or an absence of BLOOD CIRCULATION. "Taken together with the dramatically higher levels of pro-inflammatory cytokines found in KO brains at day 7, these data suggest that CD200R1 is required for resolving neuroinflammation following ischemia." (PMID 30777093, 2019).
breast tumor (4 papers, 2014 to 2025). "Cell-surface CD200 expression by mouse EMT6 breast tumor cells increased primary tumor growth and metastasis to the draining lymph nodes (DLN) in normal (WT) BALB/c female recipients, while lack of CD200R1 expression in a CD200R1-/- host negated this effect." (PMID 28234914, 2017).
chronic lymphocytic leukemia (4 papers, 2016 to 2023). "It remains unknown whether sCD200 activation of the CD200-CD200R1 pathway occurs with the same stoichiometry/efficiency as when membrane CD200 interacts with CD200R1, and this issue is currently under investigation in our chronic lymphocytic leukemia model." (PMID 27111430, 2016).
experimental autoimmune encephalomyelitis (4 papers, 2017 to 2021). An autoimmune demyelinating disease of the central nervous system that is produced experimentally in animals by the injection of homogenized brain or spinal cord in Freund's adjuvant. "By contrast, when CD200R1 is blocked, an exacerbation of microglial activation and dopaminergic neurodegeneration in 6-OHDA-treated rats has been described, as well as increased dopaminergic neuron death in the LPS model of PD and a worse outcome in experimental autoimmune encephalomyelitis." (PMID 33823877, 2021).
head and neck squamous cell carcinoma (4 papers, 2020 to 2024). A squamous cell carcinoma that arises from any of the following anatomic sites: lip and oral cavity, nasal cavity, paranasal sinuses, pharynx, larynx, and salivary glands. "CD200R1 is not only differentially expressed in non-small cell lung cancer and has a prognostic effect, but also predicts survival in patients with head and neck squamous cell carcinoma." (PMID 37858131, 2023).
non-small cell lung carcinoma (4 papers, 2021 to 2025). A group of at least three distinct histological types of lung cancer, including non-small cell squamous cell carcinoma, adenocarcinoma, and large cell carcinoma. "Unfavorable survival in non-small cell lung cancer (NSCLC) may be related to high-expressed CD200R1, whereas CD200R1 knockdown could inhibit the cancer cell proliferation." (PMID 40936767, 2025).
psoriasis (4 papers, 2020 to 2023). An autoimmune condition characterized by red, well-delineated plaques with silvery scales that are usually on the extensor surfaces and scalp. "Here, we show that contrary to this, psoriasis models are less severe in CD200R1-deficient mice due to reduced IL-17 production." (PMID 36623588, 2023). "This shows that, surprisingly, global CD200R1 deficiency reduces the severity of psoriasis-like skin inflammation due to a reduced IL-17A production." (PMID 36623588, 2023). "Here we show reduced CD200, and CD200R1 signaling in PN skin which, in a mouse model of psoriasis, results in enhanced severity associated with increased skin thickening, CCL20 levels, and neutrophil recruitment." (PMID 35759230, 2022). "To examine this hypothesis, here, we compare the severity of inflammation in psoriasis models in wild-type (WT) and CD200R1-deficient mice." (PMID 36623588, 2023). "We recently examined psoriasis-like skin inflammation in mice treated with a CD200R1 blocking antibody and found that neutrophil accumulation was increased, demonstrating that CD200R1 limits neutrophil recruitment." (PMID 36623588, 2023). "Given the reduction in IL-17A production in psoriasis-like skin inflammation models, the expression of CD200R1 on skin cells was examined." (PMID 36623588, 2023). "Given this, the relatively low level of expression of CD200R1 on dermal γδ T cells, the higher expression on ILCs, and the evidence that ILC3 contribute to human psoriasis, the effect of CD200R1 on ILCs was examined." (PMID 36623588, 2023). "Together these data show that CD200R1 blockade modestly enhances skin thickening and vastly increases neutrophil recruitment in psoriasis models." (PMID 35759230, 2022). "The role of CD200R1 in regulating psoriasis‐like skin inflammation was examined using CD200R1 blocking antibodies in mouse psoriasis models." (PMID 35759230, 2022). "We previously observed reduced CD200R1 signaling in psoriasis-affected skin, suggesting that dysregulation may promote disease." (PMID 36623588, 2023). "In mouse models of psoriasis CD200R1 was shown to limit psoriasis‐like inflammation by enhancing acanthosis, CCL20 production and neutrophil recruitment, but surprisingly, macrophage function and IL‐17 production were not affected, and neutrophil reactive oxygen species production was reduced." (PMID 35759230, 2022). "Lower levels of sCD200R1 in our patients may be due to the documented reduced expression of CD200R1, but we must also consider enhanced metalloproteinases activity in psoriasis and metabolic syndromes, which increases membrane CD200R1 shedding." (PMID 36556186, 2022). "Its receptor, CD200R1, suppresses neutrophil recruitment to skin, therefore the dysreguation of this pathway in psoriasis may promote immune responses therefore contributing to disease." (PMID 35759230, 2022). "In conclusion, we highlight CD200R1:CD200 as a pathway that might be targeted to dampen inflammation in patients with psoriasis." (PMID 35759230, 2022). "We knew that both markers CD200R1 (which may consequently lead to a reduction in sCD20R1) and sTLR2 are lower in patients with psoriasis." (PMID 36556186, 2022). "We reveal that CD200 and signaling via CD200R1 are reduced in non‐lesional psoriasis skin." (PMID 35759230, 2022). "We hypothesize that CD200R1 signaling is dysregulated in psoriasis, allowing immune responses to occur more readily." (PMID 35759230, 2022). "Therefore, targeting CD200R1 signaling may be a novel therapeutic strategy for treating psoriasis, which warrants further investigation." (PMID 35759230, 2022). "Therefore, the reduced CD200 and CD200R1 signaling in PN skin will likely lead to increased neutrophil accumulation in response to a challenge, enhancing the immune response and potentially promoting the onset of a psoriasis flare." (PMID 35759230, 2022).
psoriasis (continued). "Indeed, the skin thickening in response to psoriasis-like inflammation was not changed in CD200R1-deficient mice despite the reduction in IL-17A, which suggests that there may be an increase in an alternative inflammatory response in these mice." (PMID 36623588, 2023). "Mouse skin immune cells express CD200R1, and psoriasis‐like skin inflammation largely does not affect this expression." (PMID 35759230, 2022). "Therefore, investigating the role of CD200R1 in addition to CD200 is crucial for understanding the role of this receptor‐ligand family in regulating the human disease, psoriasis." (PMID 35759230, 2022).
Allergy (3 papers, 2015 to 2020). An allergy is an immune response or reaction to substances that are usually not harmful. "Previous studies have reported that the expression of CD200R1 on mouse basophils increases in response to antigen-specific and anti-IgE stimulation in a mouse allergy model 23, and Ba103, specific to CD200R3, has been established as a basophil-recognizing mAb 27,28." (PMID 26417442, 2015).
COVID-19 (3 papers, 2021 to 2024). A disease caused by infection with severe acute respiratory syndrome coronavirus 2. "Consistently, we observed an inverse relationship between CD200R1 serum levels and COVID-19 severity." (PMID 36012423, 2022).
depression (3 papers, 2022 to 2024). "Taken together, the development of depression is closely related to the activation of microglia and corresponding changes, and CD200/CD200R1 signaling plays an important role in maintaining microglia homeostasis." (PMID 37391731, 2023). "However, the role of CD200/CD200R1 in depression is not currently known." (PMID 37391731, 2023).
ischemic stroke (3 papers, 2019 to 2022). A stroke disorder caused by obstruction of blood flow to the brain, due to thrombotic (local blood clot formation) or embolic (due to a blood clot or other material traveling from another site) event. "To begin, we examined whether CD200R1 deficiency altered acute outcomes following experimental ischemic stroke." (PMID 30777093, 2019). "Next, we examined the expression of CD200R1 protein on brain-resident microglia and peripheral infiltrating immune cells 72 h after experimental ischemic stroke." (PMID 30777093, 2019).
asthma (2 papers, 2021 to 2025). "Combined with previous research, our study found that ECM1 and CD200R1 are risk factors for asthma, indicating that we can systematically obtain more experimental data, including GWAS and basic research, to elucidate this further." (PMID 39806440, 2025). "Our study demonstrated a causal relationship between genetic determinants, including IL1R1, IL7R, ECM1, CD200R1, ADAM19, IL-6 sRa, and Layilin (LAYN) protein levels, and asthma." (PMID 39806440, 2025). "A causal relationship exists between genetically determined protein levels of IL1R1, IL7R, ECM1, CD200R1, ADAM19, IL-6 sRa, and Layilin (LAYN) and asthma." (PMID 39806440, 2025).
colitis (2 papers, 2016 to 2021). Inflammation of the colon. "We show that by comparison with wild-type (WT) control mice, increased expression of CD200 provides protection from both acute and chronic colitis after DSS-induction, whereas severe colitis was seen in mice lacking either CD200 or CD200R1." (PMID 26841120, 2016).
diabetes (2 papers, 2021 to 2024). "Furthermore, in diabetes-related complications, CD163+ monocyte-mediated immunosuppression was potentially reduced due to the decreased expression of the immune inhibitory receptor CD200R1." (PMID 39337580, 2024).
eosinophilia (2 papers, 2019 to 2021). "We therefore propose that enhanced eosinophilia is due primarily to increased eotaxin‐2 production from CD200R1+ airway macrophages and show by its neutralisation that eotaxin‐2 plays a non‐redundant role in eosinophilic inflammation in this model." (PMID 31365119, 2019). "By manipulating CD200R1 activity, we show that it critically regulates the amplitude of eosinophilia and type 2 cytokines, but has no significant impact on cryptococcal burden or dissemination." (PMID 31365119, 2019). "Instead, the raised eosinophilia we observed in the absence of CD200R1 likely arises from the enhanced levels of eosinophilic chemoattractant cytokines IL‐5 and eotaxin‐2." (PMID 31365119, 2019). "By contrast, we demonstrate that, rather than promoting type I cytokine responses, CD200R1 blockade enhanced eosinophilia in a mouse model of Cryptococcus neoformans infection, whereas CD200R1 agonism reduced lung eosinophilia – with neither strategy completely altering fungal burden." (PMID 31365119, 2019).
glioblastoma (2 papers, 2019 to 2021). The most malignant astrocytic tumor (WHO grade IV). "Of note, murine CD200AR-L priming prior to antigen presentation to the T-cells suppressed expression of inhibitory receptor, CD200R1, rendering these cells resistant to the effects of CD200 in the glioblastoma microenvironment." (PMID 30682795, 2019).
lymphocytopenia (2 papers, 2019 to 2021). "Next, we wanted to examine the effects of the augmented lymphopenia in CD200R1 mice on susceptibility to post-stroke infection." (PMID 30777093, 2019). "Systemically, CD200R1-KO mice exhibited signs of persistent infection including lymphopenia, T cell activation and memory conversion, and narrowing of the TCR repertoire." (PMID 30777093, 2019). "CD200R1 is an inhibitory immune receptor that is expressed in myeloid cells, and it has been observed that CD200R1-KO MCAO mice developed more spontaneous bacterial lung infections than WT MCAO mice, as well as lymphocytopenia and worse functional outcomes, among other effects." (PMID 34092245, 2021).
lymphoma (2 papers, 2012 to 2021). A malignant (clonal) proliferation of B- lymphocytes or T- lymphocytes which involves the lymph nodes, bone marrow and/or extranodal sites. "The signal transduction pathways responsible for the inhibitory effects of CD200R1 engagement have only been partially described in mouse mast cells overexpressing CD200R1 differentiated in vitro and in the human lymphoma cell line U937." (PMID 22776069, 2012).
rectal cancer (2 papers, 2019 to 2025). A primary or metastatic malignant neoplasm that affects the rectum. "Our aim was to investigate the expression and localization of CD200 and its receptor CD200R1 and their clinical significance in rectal cancer patients." (PMID 30800162, 2019). "We examined the immunohistochemical expressions and localizations of CD200 and CD200R1 in 140 rectal cancer patients." (PMID 30800162, 2019). "In conclusion, we have identified CD200 and its receptor CD200R1 expression profiles and their location in tumor and tumor surrounding is, for the first time, demonstrated in rectal cancer patients." (PMID 30800162, 2019). "Our findings also suggest the extension of the therapeutic use of CD200:CD200R1 blockers to rectal cancer patients that might lead to the more effective treatment modalities." (PMID 30800162, 2019).
anal carcinoma (1 paper, 2023). "Conversely, there were a number of productive immune genes contributing to ‘defense response’ in non-recurrent anal cancer isolates such as IL4, HLA-A, CD200R1, and CD96." (PMID 37177979, 2023).
brain injury (1 paper, 2019). Acute and chronic (see also brain INJURIES, CHRONIC) injuries to the brain, including the cerebral hemispheres, CEREBELLUM, and brain STEM. "This is consistent with our finding that CD49d is upregulated on circulating CD200R1-deficient monocytes and with earlier studies that have shown increased macrophage numbers in both sterile and autoimmune models of brain injury in CD200-deficient mice." (PMID 30777093, 2019).
fungal infection (1 paper, 2019). "The role of CD200R1 signalling in fungal infection and, more broadly, Th2‐focused inflammation is yet to be determined." (PMID 31365119, 2019). "Blockade of CD200R1 enhances type I cytokine responses in many infectious and non‐infectious settings and so may promote a more protective response to fungal infection." (PMID 31365119, 2019). "In fungal infection, Th2 responses are generally deleterious, but the influence of CD200R1 is not known." (PMID 31365119, 2019).
hyperreactivity (1 paper, 2023). "TRPM4 is associated with cold airway hyperreactivity, TMEM102 and CD200R1 are involved in Th cell activation, and ST3GAL3 and B3GNT7 are associated with protecting the distal airways against destruction." (PMID 38203236, 2023).
intracerebral hemorrhage (1 paper, 2023). A cerebrovascular disorder characterized by bleeding into one or both cerebral hemispheres including the basal ganglia and the cerebral cortex. "In contrast, the reduced expression of CD200 and CD200R1 has been observed after intracerebral hemorrhage, and CD200Fc administration could attenuate BBB leakage and improve neurological functions." (PMID 37391731, 2023).
knee osteoarthritis (1 paper, 2022). "This study aimed to determine whether CD200R1 agonists, namely the protein therapeutic CD200Fc or the synthetic DNA aptamer CCS13, both known to act as anti-inflammatory agents, are able to delay the pathogenesis of injury-associated knee osteoarthritis in a murine model." (PMID 35359946, 2022).
low grade glioma (1 paper, 2021). A grade I or grade II glioma arising from the central nervous system. "Overall, we observed significant association between IGSF10 and immune checkpoint genes such as CD200R1, VSIR, CD160, CD28, BTLA, and CD40LG in several tumors including low-grade glioma (LGG) and thyroid carcinoma (THCA)." (PMID 34351868, 2021).